ATG2B (autophagy related 2B)
Description:
Lipid transfer protein required for both autophagosome formation and regulation of lipid droplet morphology and dispersion. Tethers the edge of the isolation membrane (IM) to the endoplasmic reticulum (ER) and mediates direct lipid transfer from ER to IM for IM expansion. Binds to the ER exit site (ERES), which is the membrane source for autophagosome formation, and extracts phospholipids from the membrane source and transfers them to ATG9 (ATG9A or ATG9B) to the IM for membrane expansion (By similarity). Lipid transfer activity is enhanced by WDR45/WIPI4, which promotes ATG2B-association with phosphatidylinositol 3-monophosphate (PI3P)-containing membranes.
Synonyms: C14orf103; FLJ10242; BLTP4B
Tractability: Antibody: UniProt places it where antibodies can reach, with high confidence. PROTAC: ubiquitination databases record sites on it; its protein half-life has been measured.
Gene: Protein-coding gene on chromosome 14 (96,279,195 to 96,363,341, reverse strand). Ensembl gene ENSG00000066739.
Subcellular location: Preautophagosomal structure membrane; Lipid droplet; Endoplasmic reticulum membrane
Subcellular location (Human Protein Atlas): Endoplasmic reticulum; Vesicles
Gene Ontology:
Molecular function: lipid transfer activity; protein binding; phosphatidylinositol-3-phosphate binding; protein-membrane adaptor activity
Biological process: autophagy of mitochondrion; glycophagy; pexophagy; piecemeal microautophagy of the nucleus; reticulophagy; autophagy; intermembrane lipid transfer
Cellular component: endoplasmic reticulum; lipid droplet; phagophore assembly site membrane; endoplasmic reticulum membrane; phagophore; phagophore assembly site
Genetic constraint (gnomAD): Loss-of-function variants: 88 observed, 179.36 expected, observed/expected ratio (o/e) 0.49, 90% interval 0.41 to 0.59. The upper end of that interval is the gene's LOEUF score, 0.59, which puts it in group 2 of 6, group 1 being the genes least tolerant of losing a copy. Missense variants: 1,905 observed, 2,146.6 expected, observed/expected ratio (o/e) 0.89, 90% interval 0.85 to 0.92. Synonymous variants: 727 observed, 770.04 expected, observed/expected ratio (o/e) 0.94, 90% interval 0.89 to 1.
Homologues: Orthologues: chimpanzee ATG2B (99% identical), macaque ATG2B (99% identical), dog ATG2B (94% identical), pig ATG2B (94% identical), guinea pig ATG2B (92% identical), mouse Atg2b (91% identical), rat Atg2b (90% identical), rabbit ATG2B (87% identical), tropical clawed frog atg2b (74% identical), Drosophila melanogaster Atg2 (26% identical), Caenorhabditis elegans atg-2 (22% identical), zebrafish atg2b (12% identical). Paralogues in human: ATG2A (41% identical).
Diseases named in the same sentence as ATG2B in open-access papers:
ATG2B is named in the same sentence as 48 diseases in open-access papers, as found by Europe PMC text mining. Sharing a sentence is not in itself a finding about the gene and the disease. The quoted sentences say what the papers report.
chronic lymphocytic leukemia (9 papers, 2014 to 2024). "ATG2B is a direct target of miR-130a, which inhibits autophagy and promotes cell death and chemosensitivity by downregulating ATG2B expression in chronic lymphocytic leukemia and gastrointestinal stromal tumor (GIST)." (PMID 38690279, 2024). "Another protein in the same pathway, the ATG2B was identified as a direct target of miR-130a, an miRNA that inhibited autophagy and promoted cell death in chronic lymphocytic leukemia cells." (PMID 28459042, 2017). "Therefore, together with our data herein, multiple genes in the autophagy pathway have been shown to be regulated by miRNAs, including targeting of ATG2B by miR-130 in chronic lymphocytic leukemia and ATG14 by miR-140 in multiple myeloma." (PMID 33076962, 2020). "In chronic lymphocytic leukemia cell line, miR-130a was reported to target on Atg2B." (PMID 26771516, 2016). "Additionally, miR-130a targets ATG2B and Dicer1 to inhibit autophagy and trigger the killing of chronic lymphocytic leukemia cells." (PMID 26375442, 2015). "ATG2B is also regulated by miRNA and thus affects autophagy in NSCLC and chronic lymphocytic leukemia cells." (PMID 35029026, 2022). "miR-130a also targets ATG2B and DICER1 to inhibit autophagy and trigger killing of chronic lymphocytic leukemia cells." (PMID 25544755, 2015). "In cancer, miR-130a targets MET in non-small cell lung carcinoma and can target ATG2B and DICER1 to kill Chronic Lymphocytic Leukemia cells." (PMID 24885472, 2014). "Similarly, targeting of ATG2B and DICER1 by miR-130A inhibited autophagy in chronic lymphocytic leukemia cells, and knockdown of DICER1 alone was sufficient to block autophagy in this context." (PMID 28459042, 2017). "In chronic lymphocytic leukemia (CLL), miR-130a is among the most downregulated miRNAs and its enforced expression impaired cell viability and inhibited pro-survival autophagic activity via regulation of ATG2B and DICER1." (PMID 26389804, 2015).
breast carcinoma (7 papers, 2015 to 2026). "Moreover, lower expression levels of ATG2B and c-Kit mRNA were significantly associated with worse breast cancer recurrence-free survival (RFS) and OS (all log-rank p <0.001)." (PMID 38690279, 2024). "Compared to adjacent normal tissues, breast cancer tissues had lower mRNA expression levels of ATG2B and c-Kit (p <0.001 for both)." (PMID 38690279, 2024). "In conclusion, this study revealed that rs4900321 and rs7150025 in ATG2B, rs6753785 in BCL2L11, and rs2213181 in c-Kit are associated with early breast cancer prognosis in a Chinese population." (PMID 38690279, 2024). "According to the KM plotter database, higher ATG2B mRNA expression is associated with better RFS and OS in patients with breast cancer." (PMID 38690279, 2024). "Our genetic association study indicated that putative miRNAs binding site rs4900321 and rs7150025, located at the 3′-UTR of ATG2B, had an independent impact on the risk of EBC recurrence and death, particularly in HER2-positive breast cancer." (PMID 38690279, 2024). "In our study, ATG2B was found to be a potential protective factor in ES, the same as it's in gastric and colorectal carcinomas, breast carcinoma and cutaneous squamous cell carcinoma, but opposite to non-small cell lung cancer." (PMID 35902797, 2022). "There were several ATGs like ATG8B, ATG1A and ATG2B where low expression level at transcriptomic levels resulted in poor prognosis of ER positive, Tamoxifen treated Breast cancer patients." (PMID 34621117, 2020). "Reported research indicated that ATG2B displayed low expression in breast cancer." (PMID 35992821, 2022). "Additionally, we discovered that several polymorphisms might play important roles in the progression of HER2 enriched (ATG2B rs4900321 and rs7150025) and Luminal B (c-Kit rs2213181) early breast cancer." (PMID 38690279, 2024).
non-small cell lung carcinoma (6 papers, 2014 to 2022). A group of at least three distinct histological types of lung cancer, including non-small cell squamous cell carcinoma, adenocarcinoma, and large cell carcinoma. "Recent evidence also suggested a significant association between ATG2B rs17784271 and poor local recurrence-free survival and PFS in non-small cell lung cancer after radiotherapy." (PMID 35992821, 2022). "MiR-143 inhibits cell proliferation by targeting autophagy-related 2B (ATG2B) in non-small cell lung cancer." (PMID 33402116, 2021).
bladder cancer (5 papers, 2014 to 2025). "Single nucleotide polymorphisms associated with bladder cancer progression and recurrence, in the autophagy genes ATG2B (rs3759601) and ATG5 (rs2245214), affected both the in vitro and in vivo training effect of BCG." (PMID 31447834, 2019). "ATG2B rs3759601 has been shown to have therapeutic effects on bladder cancer treated with Bacillus Calmette-Guerin." (PMID 35992821, 2022). "Finally, we demonstrate that rs3759601 in ATG2B correlates with progression and recurrence of bladder cancer after BCG intravesical instillation therapy." (PMID 25356988, 2014). "This is exemplified by the reduced responsiveness of patients with mutations in autophagy-related genes, such as autophagy-related 2B (ATG2B), to BCG immunotherapy for bladder cancer." (PMID 40005571, 2025). "Moreover, polymorphisms in autophagy genes such as ATG2B control trained immunity in both in vitro and in vivo models, as well as the non-specific therapeutic effects of BCG in patients with bladder cancer." (PMID 25356988, 2014).
gastric cancer (5 papers, 2016 to 2025). A primary or metastatic malignant neoplasm involving the stomach. "It has been previously demonstrated that frameshift mutations of ATG2B with mononucleotide repeats occur in both CRC and gastric cancer." (PMID 35992821, 2022). "In gastric cancer, SIRT1-mediated deacetylation of ATG2B enhances autophagy and invasiveness, correlating with poor prognosis." (PMID 41213956, 2025). "In gastric cancer, SIRT1 deacetylates ATG2B, enhancing its RNF5-mediated ubiquitination and degradation, thereby suppressing autophagy and promoting tumor progression." (PMID 41213956, 2025). "It has been reported that ATG2B, ATG5, ATG9B, ATG12, and ATG16L1 are closely related to gastric cancer (GC)." (PMID 37629426, 2023).
colorectal cancer (4 papers, 2022). A primary or metastatic malignant neoplasm that affects the colon or rectum. "ATG2B has been described as a predisposition gene in familial myeloproliferative neoplasms (predisposition) and has been associated to colorectal cancer." (PMID 35123435, 2022).
myeloproliferative neoplasm (3 papers, 2022 to 2025). A clonal hematopoietic stem cell disorder, characterized by proliferation in the bone marrow of one or more of the myeloid (i.e., granulocytic, erythroid, megakaryocytic, and mast cell) lineages. "A germ line copy number duplication of chromosome 14q32, which contains ATG2B and GSKIP, was identified in families with myeloproliferative neoplasm (MPN)." (PMID 34748402, 2022).
osteosarcoma (3 papers, 2020 to 2024). A usually aggressive malignant bone-forming mesenchymal neoplasm, predominantly affecting adolescents and young adults. "MiRNA-143 levels were also found to be downregulated in chemo-resistant SAOS-2 and U2OS osteosarcoma cells, leading to changes in autophagic pathways, namely via ATG2B, Bcl-2, and/or LC3-II." (PMID 31979312, 2020). "MicroRNA is also important in the formation of drug resistance of osteosarcoma, for example the miR‐143 can inhibit autophagy but the expression of miR‐143 decreases in osteosarcoma and expression of ATG2B and LC3‐II increases, which can promote autophagy to generate chemoresistance in tumors." (PMID 38800967, 2024). "Additional research studies of osteosarcoma have demonstrated that miR-375 may function through interactions with Autophagy related gene 2B (ATG2B) and Myeloid leukemia cell differentiation protein (Mcl-1)." (PMID 36674758, 2023).
breast tumor (2 papers, 2024 to 2025). "On the contrary to our findings, in a previous study on breast tumors, promoter hypermethylation of ATG9A, ATG9B, ATG2B, and ATG4D genes was linked to reduced gene expression." (PMID 40949798, 2025). "Finally, we analyzed the mRNA expression of ATG2B, BCL2L11, and c-Kit in 113 pairs of breast tumor and adjacent normal tissue samples obtained from the TCGA database." (PMID 38690279, 2024).
chronic lymphoid leukemia (2 papers, 2018 to 2019). "miR-130a has also been found to inhibit autophagy by regulating ATG2B in lymphocytic leukemia cells." (PMID 30974864, 2019). "Similarly, in chronic lymphoid leukemia, miR-130a was also widely downregulated, while ectopic re-expression could modulate cell survival programs by regulating autophagic flux through downregulating ATG2B and DICER." (PMID 29493383, 2018).
colon cancer (2 papers, 2021). "Our findings revealed that significantly lowered ATG2B levels in human colon cancer may be recovered by ATGL blockade." (PMID 34845203, 2021).
Crohn disease (2 papers, 2021 to 2022). A gastrointestinal disorder characterized by chronic inflammation involving all layers of the intestinal wall, noncaseating granulomas affecting the intestinal wall and regional lymph nodes, and transmural fibrosis. "Meanwhile, miR‐143 targets ATG2B to inhibit autophagy and increase inflammatory reactions in Crohn's disease, and miR‐1303 also regulates mycobacteria‐induced autophagy by targeting ATG2B,38, 39 which indicated that ATG2B is the direct target of miR‐130a to regulate autophagy in VSMCs." (PMID 33611856, 2021). "ATG2B was down-regulated in inflamed tissues compared to adjacent noninflamed tissues in Crohn’s disease." (PMID 35992821, 2022).
glioblastoma (2 papers, 2022). The most malignant astrocytic tumor (WHO grade IV). "In this study, we have assessed the association between glioblastoma development and polymorphism ATG2B rs3759601." (PMID 35123435, 2022). "However, significant association with glioblastoma risk was found in ATG2B rs3759601, ATG10 rs1864183 and NOD2 rs2066844." (PMID 35123435, 2022). "Here, we aimed to assess the potential association between several candidate polymorphisms in autophagy genes (ATG2B rs3759601, ATG16L1 rs2241880, ATG10 rs1864183, ATG5 rs2245214, NOD2 rs2066844 and rs2066845) and glioblastoma susceptibility." (PMID 35123435, 2022). "Our results showed a significant correlation between ATG2B rs3759601, ATG10 rs1864183 and NOD2 rs2066844 variants and higher risk to suffer glioblastoma." (PMID 35123435, 2022). "In this study, we have analyzed common polymorphisms in genes involved in autophagy (ATG2B rs3759601, ATG16L1 rs2241880, ATG10 rs1864183, ATG5 rs2245214, NOD2 rs2066844 and rs2066845) in order to evaluate their role in the susceptibility to suffer glioblastoma." (PMID 35123435, 2022).
invasive ductal carcinomas (2 papers, 2020 to 2024). "Very little is known about the role of ATG2B in cancer, but a decreased expression of this gene linked to DNA methylation in invasive ductal carcinomas might participate in BC tumorigenesis." (PMID 33488952, 2020).
laryngeal carcinoma (2 papers, 2017). Carcinoma that arises from the laryngeal epithelium. "Though only associated in ATG2B rs3759601 heterozygosity (CG), there was a statistically significant result related with a lower risk of develop laryngeal cancer." (PMID 28761177, 2017). "We found an association between the variant in ATG10 rs1864183 and a higher susceptibility to develop laryngeal cancer, ATG2B rs3759601 and pharyngeal cancer and ATG16L1 rs2241880 and oral carcinoma." (PMID 28761177, 2017).
leukemia (2 papers, 2021 to 2022). A malignant (clonal) hematologic disorder, involving hematopoietic stem cells and characterized by the presence of primitive or atypical myeloid or lymphoid cells in the bone marrow and the blood. "Here, we investigated how simultaneous loss of the Atg2b and Gskip genes affected maintenance of the pool size of HSCs in mice, as well as autophagy and gene expression in Atg2B Gskip-deficient human leukemia cell lines." (PMID 34748402, 2022). "Previously, it was reported that miR-130a targeted ATG2B and prevented autophagy in leukemia cells." (PMID 33824300, 2021).
pharyngeal cancer (2 papers, 2017). "PS method corroborated the result in the previous analyses finding an association between ATG2B rs3759601 G allele and a higher risk to suffer from pharynx cancer (p = 0.035, OR = 2.721 (1.075–6.887))." (PMID 28761177, 2017). "Atg2B rs3759601 C > G SNP in exon 25 produces a protein change p.Gln1382Glu which could result in diminished autophagy and a higher risk to suffer pharyngeal cancer in our sample." (PMID 28761177, 2017).
anemia (1 paper, 2022). A reduction in the number of red blood cells, the amount of hemoglobin, and/or the volume of packed red blood cells. "Since erythropoiesis is a matter of the highest priority in fetal hematopoiesis, and presumably in fetal development, we consider that the disturbed erythropoiesis might cause fetal liver hypoplasia and life-threatening anemia in Atg2b Gskip−/− embryos." (PMID 34748402, 2022). "Here, we show that mice lacking both Atg2b and Gskip, but not either alone, exhibited decreased hematopoiesis, resulting in death in utero accompanied by anemia." (PMID 34748402, 2022).
arteriosclerosis obliterans (1 paper, 2021). Common occlusive arterial disease which is caused by atherosclerosis. "Furthermore, to investigate clinical significance of autophagy components (LC3 II/I and ATG2B) in ASO patients, we studied human arteries tissues with arteriosclerosis obliterans (ASO) of the lower extremities and normal lower extremity artery tissues." (PMID 33611856, 2021).
colon adenocarcinoma (1 paper, 2022). "The association between ATG2B mRNA expression and various subtypes of CRC was assessed in the TISIB database (colon adenocarcinoma, P = 3.11×10-2; rectal adenocarcinoma, P = 4.95×10-2)." (PMID 35992821, 2022). "Furthermore, there were significant associations that were found in immune cell infiltration levels under various copy numbers of ATG2B both in colon adenocarcinoma and rectal adenocarcinoma." (PMID 35992821, 2022).
COVID-19 (1 paper, 2022). A disease caused by infection with severe acute respiratory syndrome coronavirus 2. "MiRNAs that were downregulated in serum of COVID-19 patients mainly target genes promoting angiogenesis (e.g., VEGFA, ANGPT2, COL4A1, FGF2, ZEB1), apoptosis, autophagy, stress response (e.g., ATG12, ATG14, ATG2B, SOD2, TXNIP), and inflammation (e.g., CXCL9, CXCL10, IL1R1, TNF)." (PMID 36032130, 2022).
endometriosis (1 paper, 2016). The growth of functional endometrial tissue in anatomic sites outside the uterine body. "Specifically, we found that transcript levels of beclin-1, ATG5, ATG4B, and ATG2B were significantly decreased in endometriotic lesions compared with uterine horns (from endometriosis-induced mice treated with PBS)." (PMID 26775710, 2016).
Ewing sarcoma (1 paper, 2024). A small round cell tumor that lacks morphologic, immunohistochemical, and electron microscopic evidence of neuroectodermal differentiation. "Conversely, ATG2B has been identified as a potential protective biomarker in Ewing’s sarcoma." (PMID 38690279, 2024).
Huntington disease (1 paper, 2024). Huntington disease (HD) is a rare neurodegenerative disorder of the central nervous system characterized by unwanted choreatic movements, behavioral and psychiatric disturbances and dementia. "Similarly, in cattle, targeted genes like ATG2B and DHRS11 of fs-cb-miRs participate in the pathways of Huntington disease and steroid biosynthesis, respectively." (PMID 38674383, 2024).
liver failure (1 paper, 2023). A liver disease characterized by the liver losing or has lost all of its function. "Rg1 improves liver failure by using regulating autophagy, ATG2B, and the PTEN/AKT pathway to suppress inflammation." (PMID 36759837, 2023).
myeloid malignancies (1 paper, 2022). "Genetic analyses of the families revealed that germ line duplication of ATG2B and GSKIP conferred a risk of familial myeloid malignancies, and overexpression of ATG2B and GSKIP in HSCs enhanced hematopoietic progenitor differentiation." (PMID 34748402, 2022).
prostate carcinoma (1 paper, 2024). A carcinoma that arises from epithelial cells of the prostate gland. "Moreover, miR-143 downregulates the autophagy-related 2B gene (ATG2B), which makes prostate cancer cells more vulnerable to radiation." (PMID 39445208, 2024).